ALB (albumin)
Diseases named in the same sentence as ALB in open-access papers (continued):
Sharing a sentence is not in itself a finding about the gene and the disease.
diabetes (continued). "In the Insulin Resistance Atherosclerosis Study, individuals with albumin-adjusted serum calcium level ≥ 9.5 mg/dl were at significantly increased risk (OR = 1.79) of developing diabetes." (PMID 25924883, 2015). "Three months after diabetes induction, diabetic mice from all genotypes showed significant weight loss as compared to control mice, increased urine albumin, and increased BUN levels as compared to controls." (PMID 25629817, 2015). "Low albumin, diabetes and low residual renal function were significant risk factors for the PD patient survival; and peritonitis was a significant risk factor for technical survival." (PMID 26121574, 2015). "The test recommended by the American Diabetes Association for diagnosing and monitoring diabetes nephropathy is the urinary albumin:creatinine ratio; however, this test performs poorly, with relatively low sensitivity and low specificity." (PMID 24667016, 2014). "A higher %ECWBIA/TBWWatson ratio tended to be associated with older age, male sex, diabetes mellitus, resistant hypertension, lower renal function, lower serum albumin levels, higher proteinuria levels, and a higher frequency of furosemide use." (PMID 25435421, 2014). "Glycated albumin has an important clinical implication, since it is involved in the damages associated with the diabetes mellitus, such as retinopathy, nephropathy, neuropathy and coronary artery disease." (PMID 24708663, 2014). "Clinical features of the patients differing in the IVS1 −397T>C estrogen receptor α polymorphism were similar with respect to age, duration of diabetes, HbA1c, BMI, albumin excretion rate, and serum creatinine level." (PMID 24523574, 2014). "Correlation analyses to determine the association between glycated albumin and other variables including insulin secretory indices and the duration of diabetes." (PMID 25265016, 2014). "For the same diabetes duration, age and puberty increase the risk for retinopathy and elevated albumin excretion rate." (PMID 24072081, 2013). "Chronic wounds are associated not only with infection, age, and diabetes, but also with decreased albumin concentrations in the wound area." (PMID 23951012, 2013). "Multiple regression analysis revealed independent association of skin AF with age, sRAGE, and albumin-creatinine ratio in patients with diabetes (R2 = 0.38)." (PMID 23671885, 2013). "While there are many factors important to diabetes control, metabolic markers of poor diabetes control such as elevated blood glucose, blood lipids, cholesterol, and urinary albumin indicate increased risk of diabetic complications." (PMID 23497486, 2013). "The risk factors for PAD are diabetes mellitus (DM), age, and serum albumin, triglyceride (TG) and serum cholesterol levels." (PMID 24093487, 2013). "There is evidence that lipid abnormalities are associated with urinary albumin excretion (UAE) in patients with diabetes." (PMID 22958709, 2012). "Diabetic DBA/2J (STZ-treated) mice assessed at 10, 15, or 18 weeks of diabetes demonstrated severe hyperglycemia, albuminuria (increased albumin/Cr), and weight loss; renal size was significantly increased at 18 weeks of diabetes." (PMID 21747824, 2011). "In a study looking at patients with chronic kidney disease undergoing hemodialysis it was found that age, diabetes, smoking, and albumin levels were independently associated with the degree of periodontitis." (PMID 18852988, 2008). "It has been previously shown that small reductions in albumin concentrations are associated with certain comorbid conditions such as liver dysfunction, cardiovascular disease or diabetes mellitus and poorer survival in the general population." (PMID 17375036, 2007). "One possibility is that the serum albumin level reflects the degree of proteinuria, a known risk factor for progression in most kidney diseases, including diabetes." (PMID 15985177, 2005).
diabetes (continued). "At the same time, inflammation within the liver associated with the pathogenesis of diabetes mellitus could be responsible for the decreased albumin levels observed concurrently." (PMID 41583543, 2026). "Restenosis risk was elevated by diabetes (OR = 1.72, 95% CI 1.28-2.31) and hypertension (OR = 1.59, 95% CI 1.04-2.44), while medical therapy with nitrates (OR = 0.20, 95% CI 0.05-0.79) and higher albumin were protective." (PMID 42020341, 2026). "We evaluated whether preoperative patient characteristics, including serum albumin level, diabetes mellitus, and ASA‐PS, were associated with the degree of postoperative gastric dilatation, as quantified by the HI." (PMID 41488836, 2026). "Furthermore, research suggests that oxidized albumin is implicated in various diseases, such as liver disease, renal failure, diabetes mellitus, cardiovascular diseases, pulmonary cancer, and Parkinson’s disease." (PMID 40699702, 2025). "Previous CHD, diabetes mellitus, and low albumin also indicated higher risk." (PMID 40600070, 2025). "Multivariate logistic regression analysis of perioperative mortality revealed that age, sex, BMI, ADL, ASA‐PS classification, alcohol consumption, diabetes mellitus, chemotherapy, radiotherapy, cN, albumin, CRP, and position at the time of MIE were significant risk factors." (PMID 40922930, 2025). "Univariable analysis identified several factors significantly associated with OS, including age (p < 0.001), diabetes (p < 0.001), glomerulonephritis (p = 0.001), diastolic blood pressure (p < 0.001), albumin-to-globulin ratio (p < 0.001), and blood glucose (p = 0.027)." (PMID 40403009, 2025). "The findings from NHANES suggest that malnutrition assessed by CONUT is significantly associated with higher diabetes prevalence in HF, which may be attributed to factors altering total cholesterol, lymphocyte count and serum albumin." (PMID 40074368, 2025). "Moreover, another important metabolic indicatorof the body is albumin, which is a protein with multiple functions associatedwith diabetes mellitus (DM), thrombosis, and inflammation." (PMID 40351679, 2025). "In “case-mix + laboratory”-adjusted logistic regression analyses, we observed that female sex, diabetes, presence of an arteriovenous fistula/graft, and lower serum albumin, IL-6, and adiponectin levels were significantly associated with the highest tertile of leptin." (PMID 41295840, 2025). "Intervention with SGLT2i also improved the biomarkers associated with diabetes complications and cardiovascular risk: HbA1c (7.1% vs. 8.4%; p < 0.001), body mass index (30.0 vs. 31.5 kg/m2; p < 0.001) and urinary albumin to creatinine ratio (4.75 vs. 11.00 mg/g; p < 0.001)." (PMID 40005325, 2025). "The top contributing features identified for the combined model through RFECV included three molecular markers—miR342, NFKB1, and miR636—and two biochemical markers the albumin-to-creatinine ratio and HDLc, indicating their strong association with diabetes progression." (PMID 40533788, 2025). "This study aimed to investigate whether low albumin levels are a risk factor for osteoporosis (OP) in patients with type 2 diabetes mellitus (T2DM)." (PMID 40297171, 2025). "In the overall patient population, ROC curve analysis was conducted for the baseline risk model, which included traditional risk factors such as diabetes, eGFR, calcium, albumin, cholesterol, and beta-blockers, along with a model enhanced by incorporating the TyG index as a categorical variable." (PMID 40799636, 2025). "After LASSO regression selection, the following 16 variables remained significant predictors of all-cause mortality, including diabetes mellitus, phosphate binders, DBP2h, albumin, phosphorus, ΔaSKNA240, VLF, LF/HF, rMSSD240, ULF240, VLF240, LF/HF240, ΔVLF240, ΔApEn240, ΔNnmean30, ΔApEn30." (PMID 41558677, 2025).
diabetes (continued). "Other risk factors for hyperkalemia include elevated urine albumin-to-creatinine ratios, diabetes mellitus, heart failure, constipation and medication use (i.e., NSAIDs, COX2-inhibitors, sulfamethoxazole-trimethoprim, beta-blockers, ciclosporin and tacrolimus)." (PMID 41464819, 2025). "Chronic inflammation secondary to underlying comorbidities such as metabolic syndrome and diabetes may also lead to lower serum albumin levels, as well as sarcopenia and malnutrition." (PMID 41431585, 2025). "Additionally, a cohort study revealed that serum albumin is associated with diabetic chronic microvascular complications, emphasizing its potential role in both the development and management of diabetes-related conditions." (PMID 40234618, 2025). "This difference arises primarily because individuals with diabetes may experience proteinuria due to diabetic nephropathy, which leads to considerable loss of serum albumin and ultimately results in hypoalbuminemia." (PMID 40013151, 2025). "However, when glycated albumin (GA) was used as a measure of glycemic control, then GA > 20% appeared to be associated with decreased survival of patients with diabetes on PD." (PMID 40430224, 2025). "These properties of serum albumin could be instrumental both the onset and development of diabetes, while also aiding in lowering the risk and slowing the progression of diabetic retinopathy, a common vascular complication of diabetes." (PMID 40234618, 2025). "Additionally, higher selenium intake was associated with greater physical activity, higher levels of albumin, uric acid, and eGFR, a lower incidence of hypertension, diabetes, CVD, cancer, and lower total cholesterol levels." (PMID 39328467, 2024). "In the univariate analysis, factors such as age exceeding 80 years (OR, 1.6; 95% CI 1.12–2.28, P = 0.01), intertrochanteric fractures, the presence of diabetes, and admission with low albumin levels were found to be associated with an increased risk of SII levels equal to or exceeding 1621.92." (PMID 38321497, 2024). "Univariate analysis revealed that gender, the number of comorbidities (hypertension, diabetes mellitus, coronary heart disease and chronic obstructive pulmonary disease), postoperative serum albumin, tumor location, duration of operation were risk factors associated with EJAL." (PMID 39669366, 2024). "The most common risk factors reported were cardiovascular disease, older age, lower body mass index, cause of kidney disease, cancer, diabetes, lower serum albumin, faster decline in kidney function and fewer number of nephrology visits prior to dialysis start." (PMID 39669010, 2024). "Specifically, we tested the hypothesis that albumin excretion within the normal reference range among normoglycemic, normotensive persons is associated with cardiometabolic risk markers and pre-diabetes." (PMID 38233076, 2024). "Elevated levels of miR-7977 may target and degrade G6PD, thereby inhibiting albumin-induced autophagy in diabetes and potentially playing a crucial pathogenic role in the development of DKD." (PMID 39140974, 2024). "Diabetes Subcluster B, which had a higher risk of periodontitis, was characterized mainly by a smoking habit, a lower education level, a higher income-to-poverty ratio, and higher ALB and ALT levels." (PMID 39632553, 2024). "Moreover, our study elucidated the anti-glycation effects of AqLs across multiple stages of albumin glycation, highlighting its potential in mitigating the harmful effects of protein glycation associated with diabetes and aging." (PMID 39539624, 2024). "The linear regression analysis results proved that sex, diabetes mellitus, and albumin level are independently related to 25(OH)D level, while age, sex, race, diabetes, current smoking, and BMI are all independently associated with 25(OH)D deficiency in the general population." (PMID 38652006, 2024).
diabetes (continued). "In addition to age, male sex, low BMI, elevated HbA1c, diabetic nephropathy, and low serum albumin concentration have been reported as risk factors associated with low muscle strength in patients with diabetes." (PMID 39693147, 2024). "While age, diabetes mellitus, smoking, systolic blood pressure, and serum C-reactive protein concentration were positively associated with CI, intradialytic weight gain, body mass index, and serum albumin level were negatively associated." (PMID 38225279, 2024). "Normal albumin was associated with comorbid diabetes (P = 0.007)." (PMID 38972926, 2024). "A sensitivity analysis of multiple risk factors for postoperative incision infections in colorectal cancer patients revealed significant impacts on the risk of incision infections by BMI ≥24 kg/m2, diabetes, low albumin levels, laparoscopic surgery, and preoperative malnutrition." (PMID 39193402, 2024). "Likewise, the stimulation of intracellular and extracellular accelerators, like oxidative stress, and amyloid fibril creation of serum albumin upon interaction with antioxidants caused various illnesses like diabetes, obesity, and gastric cancers." (PMID 39479655, 2024). "As a result, serum albumin deficiency may increase oxidative stress and inflammation, which are major contributors to diabetes and its complications." (PMID 39796544, 2024). "In addition, old age, diabetes mellitus, deep venous thrombosis, thymic cancer, longer length of hospital stay, plasmapheresis, lower levels of hemoglobin, potassium, magnesium and albumin, and prolonged aPTT were associated with recurrent infection." (PMID 37400755, 2023). "In the multivariate linear regression analysis for all CKD participants, age, diabetes, and serum albumin showed significant associations with both hands ESC (β in model 2: −0.40, −4.89, and 7.62, respectively) and feet ESC (β in model 2: −0.38, −7.27, and 8.80, respectively)." (PMID 38202194, 2023). "Interestingly, the rs1801282 (Pro12Ala) PPARG variant associated with increased PPARG expression and reduced risk for diabetes and circulating triglycerides also associates with reduced albumin levels." (PMID 36413406, 2023). "Taking age, diabetes and serum albumin levels as independent variables, and intracranial atherosclerosis as dependent variables, binary Logistics analysis showed that diabetes and serum albumin levels were independent risk factors for intracranial atherosclerosis (P < .05)." (PMID 37210474, 2023). "A systematic review found out Female sex, diabetes, advanced age, Duration of surgery and preoperative serum albumin level as the risk factors for developing PI in cardiac surgical patient that it needs to consider for PI prevention before and during the surgery." (PMID 36938142, 2023). "After almost 4 years of follow-up, adjusting for traditional risk factors (age, sex, diabetes, smoking, albumin level, etc.), we found that CVC was an independent risk factor for all-cause mortality but not cardiovascular mortality in IHD patients, with an HR of 2.14." (PMID 36792978, 2023). "In contrast to the protective effect of dietary Ca on diabetes, a meta-analysis of four studies indicated that both total serum Ca (RR: 1.38, 95% CI: 1.15–1.65) and albumin-corrected Ca (RR:1.29, 95% CI:1.03–1.61) were associated with incident diabetes, which was in line with ours." (PMID 38125730, 2023). "Factors related to frailty, sarcopenia and cachexia (including weight loss, low body mass index, dyspnea, diabetes, serum albumin, hematocrit, and creatinine) were shown to be associated with increased risk of PPCs, wound complications, major AEs and death following HNC surgery." (PMID 36703217, 2023). "Urinary albumin excretion is a clinically relevant marker, as it is associated with the development and progression of diabetic nephropathy, another common complication of diabetes." (PMID 37373782, 2023).
diabetes (continued). "The following factors were investigated: basic clinical characteristics (age, gender), personal history (smoking, drinking), underlying diseases (diabetes, hypertension), injury type (open injury, central nervous injury), blood biochemistry (albumin level, hemoglobin level)." (PMID 36750600, 2023). "In addition to traditional CV risk factors (age, diabetes), risk factors such as decreases in eGFR values and serum albumin and history of CVD, PVD, or cerebrovascular disease were associated with increased mortality and CV event risk in this population." (PMID 37289366, 2023). "Risk factors for 90-day mortality were RDW/albumin ratio at postoperative day 1, age, American Society of Anesthesiologists physical status, diabetes mellitus, inhalation injury, total body surface area burned, hypotensive event and red blood cell transfusion volume." (PMID 35097135, 2022). "Diabetes may be associated with impaired liver production of albumin because insulin is an important regulator of its synthesis." (PMID 35831938, 2022). "Diabetes caused a sharp increase in proteinuria (urine albumin mg/24 h), ketonuria, urine specific gravity, blood urea and creatinine, which was significantly (p ≤ 0.0036) ameliorated by metformin to levels still significant (p ≤ 0.0225) to the control group for specific gravity and creatinine." (PMID 35884947, 2022). "Although the age subgroup analysis was not statistically significant, since the elderly population is inherently at higher risk of diabetes, low albumin, and vitamin D deficiency, the consequences of malnutrition risk could be more severe for them." (PMID 36558436, 2022). "In this real-world, perspective, observational study on a large-scale cohort from China with 5-year follow-up, we examined the prognostic association of type 2 diabetes mellitus with adverse outcomes in patients with different level of the fibrinogen-to-albumin ratio." (PMID 35313877, 2022). "The risk of all-cause death was significantly associated with older age, low BMI, diabetes mellitus, low levels of hemoglobin, albumin, and creatinine, the higher half of IL-6, past history of CVD, and malignancy in the unadjusted Cox proportional hazards model." (PMID 35155493, 2022). "A univariate analysis was conducted with sex, age, smoking history, history of diabetes, cause of injury, Sanders type, tension blisters, time from injury to surgery, preoperative haemoglobin, preoperative albumin, operation time, and bone grafting as possible risk factors." (PMID 36514037, 2022). "Bivariate analysis showed that age, duration of diabetes, smoking, cardiac comorbidity, hypertension, neuropathy, dyslipidemia, eGFR, HbA1C, albumin level, and neutrophil lymphocyte ratio were associated with mortality within one year after endovascular revascularization." (PMID 35300753, 2022). "Diabetes, lower albumin and higher FIB-4 were associated with a higher risk of a first LRE." (PMID 36061511, 2022). "Further, the 2021 recommendations from the American Diabetes Association include albumin and estimated glomerular filtration rate (eGFR) monitoring annually and, for patients with urinary albumin > 300 mg/g creatinine and/or eGFR 30-60 mL/min/1.73m2, monitoring twice annually." (PMID 35948873, 2022). "We also evaluated if, independently of diabetes mellitus, plasma glucose levels on admission may modify the association of albumin levels with <30 days all-cause mortality in COVID-19 patients." (PMID 35160039, 2022). "However, DOAC therapy was independently associated with lower mortality after adjustments for age, diabetes mellitus, and albumin level (hazard ratio, 0.55; 95% confidence interval, 0.30–0.99; p = 0.045) in the eGFR < 45 mL/min/1.73 m2 subgroup." (PMID 35064298, 2022). "Glycated albumin and fructosamine are alternative markers of glycemia that can be monitored (usually by endocrinologists) at baseline and every 2 weeks for patients at high risk for diabetes." (PMID 35016012, 2022).